MBD3L5 (methyl-CpG binding domain protein 3 like 5)
Tractability: No criterion of Open Targets' tractability assessment is met for any kind of drug.
Gene: Protein-coding gene on chromosome 19 (7,030,578 to 7,033,011, forward strand). Ensembl gene ENSG00000237247.
Subcellular location (Human Protein Atlas): Nucleoli; Nucleoplasm; Cytosol
Gene Ontology:
Molecular function: methyl-CpG binding
Biological process: DNA methylation-dependent constitutive heterochromatin formation; negative regulation of transcription by RNA polymerase II
Cellular component: nucleus
Homologues: Orthologues: rat Mbd3l2 (43% identical), rat Mbd3l3 (40% identical), mouse Mbd3l2 (39% identical), zebrafish mbd3a (31% identical), tropical clawed frog mbd3 (31% identical), Drosophila melanogaster MBD-like (22% identical). Paralogues in human: MBD3L4 (99% identical), MBD3L2 (99% identical), MBD3L3 (99% identical), MBD3L2B (97% identical), MBD3L1 (35% identical), MBD2 (32% identical), MBD3 (32% identical), MBD1 (21% identical).